SND1 (staphylococcal nuclease and tudor domain containing 1)
Diseases named in the same sentence as SND1 in open-access papers (continued):
Sharing a sentence is not in itself a finding about the gene and the disease.
cancer (continued). "However, the effect of circRNAs on transcriptional coactivation function of SND1 in cancer progression remains to be investigated." (PMID 35659274, 2022). "In the present study, we demonstrate that AEP specifically cleaves Tmod3 at N157 and produces two truncated Tmod3 proteins, which regulate the invasion and proliferation of cancer cells through cytoplasmic actin remodeling and nuclear SND1/RhoA signaling, respectively." (PMID 35765111, 2022). "Indeed, inhibiting SND1’s RNA binding capability with novel SND1 inhibitor suramin sensitizes cancer cells to navitoclax treatment." (PMID 35804872, 2022). "Thus, we wanted to analyze the effect of SND1 silencing on the apoptotic effect of 545 cancer drugs that target the main cancer related signaling pathways." (PMID 35804872, 2022). "tTmod3-C is accumulated in the nucleus and enhances SND1-mediated cancer cell proliferation." (PMID 35765111, 2022). "By establishing a novel screening assay, we have identified inhibitors for SND1–RNA interaction and shown that the inhibition of RNA-binding sensitizes cancer cells to navitoclax, possibly by preventing the SND1-mediated miRNA degradation of tumor suppressor miR-1-3p." (PMID 35804872, 2022). "Recently, SND1 has gained attention due to its high expression of protein level in several cancers." (PMID 36213325, 2022). "Overexpression of SND1 has been detected in various cancer types in TCGA." (PMID 35659036, 2022). "Another study has suggested SND1 implication in cell motility, one of cancer cells’ hallmarks." (PMID 34809722, 2021). "Like PRMT5, SND1 is upregulated in many different cancer types." (PMID 33768972, 2021). "It is intriguing that SND1 plays a role in regulating both inflammation and lipid metabolism, and also the hallmarks of cancer by a variety of mechanisms, suggesting that targeting SND1 might be a viable option for HCC." (PMID 32258418, 2018). "These multifaceted properties allow SND1 to positively impact all hallmarks of cancer, notably sustaining proliferative signaling, evading growth suppressors, resisting cell death, enabling replicative immortality, inducing angiogenesis, and activating invasion and metastasis." (PMID 32258418, 2018). "Contribution of SND1 and SREBPs to lipid metabolism reprogramming in cancer cells may be, otherwise, expected in view of the report illustrating that deregulated cholesterol homeostasis and SREBP-2 activity is associated with SND1 overexpression." (PMID 30619748, 2018). "Is SND1 overexpression alone sufficient for transforming normal cells into cancer cells?" (PMID 25405367, 2015). "Overexpression of SND1 has been observed in breast, prostate, colon and brain cancer." (PMID 26323317, 2015). "An SND1 knockout mouse, conditional and global, will not only provide comprehensive insights into the physiological functions of SND1, but also will be an ideal model to interrogate the role of SND1 in immortalization, transformation, metastasis and overall cancer development and progression." (PMID 25405367, 2015). "However, since SND1 exerts oncogenic effects in selected cancers, treating patients with cancer by overexpressing SND1 may not be feasible." (PMID 39895626, 2025). "Thus, targeting KDM6A and/or disrupting the interaction between KDM6A and SND1 could represent a promising therapeutic strategy for cancer treatment and overcoming the chemoresistance bottleneck." (PMID 38850159, 2024). "In addition, the expression of SND1 often correlates with the malignant state of the cancer." (PMID 35804872, 2022). "Moreover, ABS affects the potential targets on cancer therapy such as SND1, KPNA2, and PARK7." (PMID 31240215, 2019). "The Cancer Genome Atlas and NCBI Gene Expression Omnibus (GEO) databases were used to evaluate SND1 expression levels in PCa." (PMID 40775338, 2025).
cancer (continued). "The interaction between MTDH and SND1 is essential for the function of MTDH in tumor-initiating cells, suggesting their pivotal role in cancer progression and potential as therapeutic targets." (PMID 41286067, 2025). "Staphylococcal nuclease domain-containing protein 1 (SND1) is an evolutionarily conserved multidomain protein, which has gained attention recently due to its positive regulation in several cancer progression and metastatic spread." (PMID 36213325, 2022). "SND1 attracted our attention because its 3′-UTR contains a putative target sequence for miR-361-5p, and SND1 is closely involved in cancer cell migration and invasion." (PMID 25965817, 2015). "Furthermore, various studies have identified SND1 as a crucial binding partner of MTDH, highlighting its significant role in cancer metastasis and chemoresistance." (PMID 41286067, 2025). "SND1, a multifunctional protein and a key nuclease in several processes including RISC regulating transcription, mRNA splicing, and miRNA-mediated mRNA degradation, etc., is ubiquitously overexpressed in cancers where it generally functions as an oncogene." (PMID 39885142, 2025). "The interplay between SND1 and lncTCF7 in GBM may provide insight into broader mechanisms of gene regulation in cancer." (PMID 39169000, 2024). "SND1 and MTDH are known to promote cancer and therapy resistance, but their mechanisms and interactions with other oncogenes remain unclear." (PMID 37973913, 2023). "In summary, PRMT5 is a key regulator of RNA splicing, and as an effector molecule for SDMA marks deposited by PRMT5, it is not surprising that SND1 is also integral to the maintenance of normal splicing programs that can go awry in a cancer setting." (PMID 33768972, 2021). "In-situ hybridization of randomly selected samples from the IHC-analyzed cohort showed consistently elevated SND1-mRNA in cancer cells and low or negative expression in the normal counterparts." (PMID 34809722, 2021). "Given its role in regulating a wide variety of cellular properties, it comes as no surprise that SND1 functions as an oncogene in a variety of cancers, including breast, liver, lung, gastric, glial, prostate and colorectal cancer." (PMID 32258418, 2018). "In prostate cells, SND1 recruits splicing factor SAM68 and other spliceosomal components on CD44 pre-mRNA, promotes the inclusion of CD44 variable exons, which correlates with increased proliferation, motility, and invasiveness of cancer cells." (PMID 26808625, 2016). "The level of SND1 mRNA was found to be higher in cancer tissues than in corresponding non-cancer tissue in which the level of miR-361-5p is high." (PMID 25965817, 2015). "W394 and W401 were identified as key residues of AEG-1 interacting with SND1, and the crystal structure of the AEG-1/SND1 interaction region was resolved, paving the way for developing small molecule inhibitors that perturb this interaction, inhibit AEG-1, and serve as anti-cancer agents." (PMID 40282551, 2025). "In addition, proteins that have been related to other cancers but not to BC yet, were also identified, such as fibulin-2 (FBLN2), tissue alpha-L-fucosidase (FUCA1), staphylococcal nuclease domain-containing protein 1 (SND1), and EIF3D." (PMID 29050215, 2017).
tumor (59 papers, 2011 to 2025). "Of note, SND1 knockdown significantly reversed the promotion of tumor growth caused by SPT6 overexpression." (PMID 33305480, 2021). "While numerous studies have established that SND1 protein expression is modulated by cellular stresses associated with tumor growth, hypoxia, inflammation, heat-shock and oxidative conditions, little is known about the factors responsible for SND1 expression." (PMID 25494629, 2014). "Among these apoptotic genes, PDCD4, a critical tumor suppressor gene that encodes a pro-apoptotic protein, which stimulates apoptosis via the inhibition of procaspase-3 mRNA translation, was identified to be upregulated by SND1 silencing at the gene level." (PMID 39885142, 2025). "The interaction of SND1 with mRNAs and miRNAs may be of notable relevance in cells undergoing a tumor growth-associated stress because of the potential contribution to angiogenesis regulation." (PMID 25494629, 2014). "In subcutaneous transplantation models, stable SND1 KD significantly inhibited tumor growth in vivo." (PMID 40775338, 2025). "Regarding the role of SND1 in tumors, it has been reported that SND1 promotes tumor growth by activating Wnt signaling." (PMID 40775338, 2025). "In mouse studies, SND1 has been shown to promote tumor angiogenesis by activating NF-κB and inducing anigogenin." (PMID 41226545, 2025). "The overexpression of AEG-1 or SND1 augmented RISC activity with a resultant increased degradation of tumor-suppressor mRNAs targeted by oncogenic miRNAs, e.g., there was downregulation of PTEN which is a target of miR-221, an oncogene for HCC." (PMID 40282551, 2025). "Staphylococcal nuclease-containing structural domain 1 (SND1), which is a transcriptional co-activator, is considered as a promising target for tumor therapy." (PMID 38296623, 2024). "In this study we identified a significant impact of SND1 on the regulation of mRNA levels; however, future studies will have to assess the significance of these changes with respect to tumor promotion." (PMID 37973913, 2023). "Taken together, these findings establish a previously unappreciated role of SND1 and the association of mitochondrion-localized SND1 with PGAM5 in mitophagy and tumor progression." (PMID 35433434, 2022). "By performing cell growth and xenograft assays, we find that SND1-induced mitophagy promotes cell proliferation and tumor progression, depending on PGAM5 and its mitochondrial localization." (PMID 35433434, 2022). "PGAM5 and the MTS of SND1 are required for SND1-promoted mitophagy, cell proliferation, and tumor growth." (PMID 35433434, 2022). "Immunoblotting using tumor tissue lysates confirmed the overexpression of SND1 and the knockdown of PGAM5 by shRNAs in Hep3B xenografts." (PMID 35433434, 2022). "As previously reported, stable overexpression of SND1 promoted cell proliferation and tumor growth in Hep3B cells compared with the control empty vector group." (PMID 35433434, 2022). "Using tumor tissue lysates, we further confirmed the knockdown of endogenous SND1 and overexpression of wild-type SND1 and the SND1Δ1-63 mutant." (PMID 35433434, 2022). "For example, SND1-MTDH interaction regulates tumor formation, recurrence, metastasis, and sensitivity to chemotherapeutics in mouse mammary tumor models." (PMID 35804872, 2022). "The activation of the NF-κB pathway by SND1 overexpression is reported to increase oncogenic miRNAs (oncomiRs) such as miR-221, that target and degrade tumor suppressor RNAs." (PMID 33768972, 2021). "WB and IHC analysis showed the high expression of SND1 and hTERT in tumor tissues compared to the adjacent normal tissues." (PMID 33305480, 2021). "The expression correlation and clinical significance of SPT6, SND1, and hTERT were investigated in tumor tissues from murine models and patients with CRC in situ." (PMID 33305480, 2021).
tumor (continued). "Deletion of SND1 in tumor mouse models restores tumor antigen presentation to T cells both in vitro and in vivo and enhances T cell infiltration into the tumors." (PMID 33406696, 2021). "The melanoma B16F10 cell line has been used to investigate the role of SND1 in facilitating immune evasion of tumor cells." (PMID 33768972, 2021). "As a component of the RISC in HCC cells, SND1 promotes oncogenic miRNA-mediated degradation of tumor suppressor mRNAs." (PMID 32258418, 2018). "Emerging information from plants and animal cells has demonstrated that SND1 protein expression changes in response to cellular stresses related to inflammation, tumor growth, hypoxia, heat shock, oxidative conditions, and DNA damage." (PMID 30619748, 2018). "This notion is strengthened by the observation that Alb/SND1 mice develop spontaneous HCC, thus establishing SND1 as a tumor driver." (PMID 32258418, 2018). "On the other hand, SND1 overexpression significantly abrogated the inhibitory effect of miR-361-5p on cell proliferation, suggesting that miR-361-5p exerts tumor-suppressive function in CRC via directly binding to SND1." (PMID 25965817, 2015). "And its overexpression was negatively correlated with the SND1 expression and the status of tumor metastasis." (PMID 25965817, 2015). "The present study is the first to demonstrate that miR-361-5p functions as a tumor-suppressive miRNA through directly binding to SND1 in CRC and GC." (PMID 25965817, 2015). "Proteins important for tumor cell survival (SND1), proteins known to be expressed by MM cells (PPA1, CCT3, NME1, SPAG9), and a marker for bone resorption (DPYD) were detected at higher levels in the NBM coculture supernatants." (PMID 26545722, 2015). "SND1 also augmented tumor angiogenesis by activating NF-κB which induces miR-221 and angiogenic factors Angiogenin and CXCL16." (PMID 25965817, 2015). "A recent study showed that MTDH played a critical role in mammary tumorigenesis by regulating oncogene-induced expansion and activities of tumor-initiating cells (TICs) through interacting with SND1." (PMID 25333261, 2014). "Additionally, SND1 has been reported to participate in regulating RNA alternative splicing, maturation, and stability, thereby promoting tumor progression." (PMID 40775338, 2025). "In conclusion, SND1 KD suppressed tumor growth and metastasis in vivo." (PMID 40775338, 2025). "Together, these results suggest that XBP1s‐induced tumor progression and drug resistance may be a consequence of the transcriptional activation of SND1." (PMID 40940685, 2025). "Additionally, an early report indicates that MTDH S-palmitoylation suppresses its interaction with SND1, thereby inhibiting tumor growth of HCC." (PMID 41318030, 2025). "In this regard, other alternative or predominant tumor suppressors/apoptotic modulators may play a bigger role in SND1 silencing-induced chemosensitivity in NSCLC cells." (PMID 39885142, 2025). "SND1 can also induce hepatic tumour-initiating cells forming via regulating Akt signalling." (PMID 37885030, 2023). "SND1 has been shown to promote tumor development in many tumors." (PMID 37893001, 2023). "Furthermore, SND1 (chromosome 7) exerts a cis-effect on protein level and was associated with the activation of STAT3, which was relevant to tumor proliferation." (PMID 35659036, 2022). "To address whether PGAM5-mediated mitophagy and mitochondrial localization of SND1 are necessary for SND1 regulation of cell proliferation and tumor growth, we performed cell growth assays and xenograft experiments using Hep3B cells." (PMID 35433434, 2022). "In conclusion, we revealed the previously unknown localization of SND1 to mitochondria, which regulates mitophagy, cell growth, and tumor progression." (PMID 35433434, 2022).
tumor (continued). "Importantly, we demonstrate that PGAM5 and SND1-MTS are required for SND1-mediated mitophagy under FCCP and glucose deprivation treatment as well as for SND1-mediated cell proliferation and tumor growth both in vitro and in vivo." (PMID 35433434, 2022). "Finally, although genes become nested by random, it is interesting to note that SND1 is an oncogene and Lrcc4 is a tumor suppressor." (PMID 36566329, 2022). "SND1 promoted the expansion of tumor-initiating cells (TICs) in Alb/SND1 mice." (PMID 33918653, 2021). "In addition to these, we next explored the synergy between SPT6 and SND1 in regulating the sensitivity of tumor cells to chemotherapeutics." (PMID 33305480, 2021). "Thus, the miR-361-5p/SND1 feedback loop provides a new avenue to understand the mechanism of the tumor invasion and metastasis in CRC and GC." (PMID 25965817, 2015). "So far, the SND1 overexpression that occurs in multiple types of cancer cells has been interpreted to mean parallel activation of the RNA-induced silencing complex activity and degradation of tumor suppressor mRNAs." (PMID 25494629, 2014). "Thus, high levels of SND1 helps tumor cells evade cell death." (PMID 33768972, 2021). "Therefore, it could be concluded that miR-361-5p functions as a tumor-suppressive miRNA through directly binding to SND1, highlighting its potential as a novel agent for the treatment of patients with CRC and GC." (PMID 25965817, 2015). "Conversely, in tumor cells with MTDH KD, the binding of SND1 to SESN2 was notably weakened, indicating the crucial role of MTDH in promoting the SND1-SESN2 interaction." (PMID 40775338, 2025). "Currently, the use of SND1 inhibitors (such as pdTp) or miR-142-3p antagonists has been identified as a strategy to upregulate PTPN23, thus inhibiting tumor growth." (PMID 40570022, 2025). "AEG-1-C75A displayed increased AEG-1 protein stability, stronger interaction with SND1, and augmented RISC activity, resulting in the downregulation of tumor suppressor mRNAs." (PMID 40282551, 2025). "BLI imaging exhibited that tumor inhibition was more prominent when erastin treatment combined with SNAI3-AS1 overexpression, and such effect was impaired followed by SND1 overexpression." (PMID 37202791, 2023). "Accordingly, circSMARCA5 can inhibit the interaction of SND1 and YWHAB, and can also reduce the level of SND1, thereby exerting a tumor suppressor effect." (PMID 35712125, 2022). "In agreement, such scenario was supported by our observations that stabilized AEG-1 (AEG-1C75A) enhances its binding to SND1 and activates RISC activity for the downregulation of these tumor suppressors and HCC progression." (PMID 36276642, 2022). "Other low frequency actionable fusions namely, AGK-BRAF, FIP1L1-PDGFRA, FNDC3B-PIK3CA, RET-NCOA4, SND1-BRAF, TMEM178B-MET, TMEM178B-BRAF, KANK1-NTRK3, EIF3E-RSPO2 and PTPRK -RSPO3 have been previously reported as rare fusions in tumours of other type." (PMID 35984852, 2022). "To further confirm the synergy between SPT6 and SND1 in affecting tumor progression in vitro, we overexpressed or knocked down SPT6 and SND1 at the same time and evaluated their effects on the cell viability and sphere‐forming ability." (PMID 33305480, 2021). "First, SND1 can regulate cellular cholesterol distribution and homeostasis in HCC cells and promote tumor-initiating cell (TIC) formation via the Akt and NF-κB signaling pathways in Alb/SND1 mice." (PMID 34692544, 2021). "In HCC cells, SND1 activates NF-κB, resulting in induction of miR-221 and angiogenic factors angiogenin and CXCL16 that promote tumor angiogenesis." (PMID 32258418, 2018). "SND1 interacts with and inhibits monoglycerolipid lipase (MGLL), a tumor suppressor that converts monoglycerolipids to glycerols and free fatty acids." (PMID 32258418, 2018). "miR-361-5p overexpression inhibited tumor growth and metastasis in CRC and GC cells through the down-regulation of SND1." (PMID 25965817, 2015).